HSPE1 (heat shock protein family E (Hsp10) member 1)
Diseases named in the same sentence as HSPE1 in open-access papers (continued):
Sharing a sentence is not in itself a finding about the gene and the disease.
cancer (26 papers, 2005 to 2026). A tumor composed of atypical neoplastic, often pleomorphic cells that invade other tissues. "HSPE1 had been found to be aberrantly expressed in various cancers and was associated with poor prognosis." (PMID 41035644, 2025). "Among the up-regulated genes, we observe the proto-oncogene FOS62 as well as a set of other cancer-related genes such as HSPE1, TXN and TXNIP." (PMID 29434270, 2018). "In this study, immunohistochemical analyses showed that HSPE1 is overexpressed in BC compared with adjacent normal tissue; similar overexpression of HSPE1 in tumor cells has also been reported in other cancers." (PMID 30112103, 2018). "The heat shock protein HSPE1 has been previously suggested to be involved in cancer etiology and is overexpressed in exocervical carcinoma as well as in colon cancer." (PMID 29434270, 2018). "The presence of HSPE1 has been reported in B-cell derived sEVs and cancer cell-derived EVs by mass spectrometric analysis, but the function of EV-associated HSPE1 has not been evaluated." (PMID 31337116, 2019). "For example, knockout of HSPE1, HSPA9, and DNAJC9 significantly reduced cell proliferation across 21 cancer cell lineages." (PMID 33225964, 2020).
tumor (23 papers, 2005 to 2026). "The ability of HSPE1 to differentiate BC was accessed by a receiver operator curve (ROC) analysis of clinical tumor tissue." (PMID 30112103, 2018). "There is also evidence that HSPE1 may play different roles in tumor cells, with some previous studies reporting that differential expression of HSPE1 contributes to tumor survival, tumor progression, and suppression of antitumor immunity." (PMID 30112103, 2018). "There are indications that HSPE1 might undertake diverse roles within tumor cells." (PMID 38017020, 2023). "First, our study showed that naïve T-cells in tumor tissues exhibit increased expression of HSPs, including HSPD1, HSPE1, HSPA1A, HSPA6, and DNAJB1." (PMID 41186645, 2026). "Of this group of genes, HSPD1, HSPE1, CCT3 and CCT5 were overexpressed in Basal, HER2 and Luminal B subtypes (more aggressive BRCA tumours)." (PMID 29954368, 2018). "The elevated expression of HSPs such as HSPD1, HSPE1, HSPA1A, HSPA6, and DNAJB1 suggests that naïve T-cells in tumor tissues may be under a state of stress or heat shock." (PMID 41186645, 2026). "Non-histone chromosomal protein HMG-17 (HMGN2), thymosin beta-4 (TMSB4X), 10 kDa heat shock protein (HSPE1), and the ratio between citrullinated/uncitrullinated GFAP fragment 388–432 showed significantly higher levels in ST-EPs, therefore marking the ST tumor location." (PMID 32183175, 2020).
neurodegenerative disease (3 papers, 2019 to 2026). A disorder of the central nervous system characterized by gradual and progressive loss of neural tissue and neurologic function. "Further, HSPE1 (Hsp10 gene) mutation is linked to neurodegenerative diseases, supporting the hypothesis that a dysregulation of the MSR is detrimental to brain health." (PMID 33946318, 2021).
HSPE1 also shares sentences with these, for which no sentence is quoted: infection (14 papers); large bowel cancer (4); astrocytoma (3); bacterial infection (3); lung carcinoma (3); neuroblastoma (3); periodontitis (3); tuberculosis (3); Alzheimer disease (2); atherosclerosis (2); autoimmune disease (2); chronic obstructive pulmonary disease (2); coronary atherosclerosis (2); Insulin resistance (2); mantle cell lymphoma (2); melanoma (2); nasopharyngeal carcinoma (2); neurological diseases (2); oral squamous cell carcinoma (2); pancreatic cancer (2); synucleinopathies (2); urticaria (2); African sleeping sickness (1); amyloid disease (1); anthrax infection (1); asthma (1); Autoimmunity (1); benign tumors (1); brucellosis (1); carcinosarcoma (1).
A further 43 diseases each share a sentence with HSPE1 in 1 paper.